SOX2 (SRY-box transcription factor 2)
Diseases named in the same sentence as SOX2 in open-access papers (continued):
Sharing a sentence is not in itself a finding about the gene and the disease.
glioma (continued). "The present study aimed to quantify the expression profiling of longevity-related transcriptional factors SOX2, OCT3/4, and NANOG to evaluate their diagnostic and performance values in high-grade gliomas." (PMID 29849920, 2018). "Results from three independent experiments are shown for Sox2 and Olig2 V5 tagging using mouse neural stem (NS) and glioma-initiating neural stem (GNS) cells." (PMID 29638216, 2018). "Considering the strong association between the high SOX2 level and glioblastoma development, some researchers believed that SOX2 can be a target for glioma therapy in future." (PMID 30053878, 2018). "In comparison with the paired glioma cultures derived in serum containing medium, the serum-free medium derived cells expressed significantly more Sox-2, the stemness marker crucial for the tumorigenicity of GSCs32, on both mRNA and protein levels." (PMID 29434344, 2018). "Silencing of MALAT1 suppressed the proliferation and stemness of GSCs and in vivo tumour growth via up‐regulating miR‐129 and further inhibiting SOX2, providing a promising therapy target for the treatment of glioma." (PMID 29808528, 2018). "According to some authors, SOX-2 knockdown indeed strongly affects the sphere generation capacity in glioma cell cultures, the dedifferentiation rate, and the stemness phenotype, thus reducing tumorigenicity." (PMID 30227679, 2018). "Although NEAT1, miR-132 and SOX2 have been proved to play crucial roles in glioma, their regulatory mechanism and interaction still need to be further studied." (PMID 30053878, 2018). "Previous study showed that TGF-β induces the self-renewal capacity of glioma stem cells (GSCs) and increases the expression levels of stemness-related factors Musashi1 and Sox2." (PMID 29467947, 2018). "In U251 and U87 glioma cells, si-SOX2 transfection significantly reduced the expression level of SOX2." (PMID 30053878, 2018). "We also checked the expression of SOX2, a neural stem cell marker, and found that SOX2 mRNA expression levels were also up-regulated in gliomas." (PMID 29137410, 2017). "Given the fact that CMV persistence of GSC is associated with high expression of SOX2 and induction of neurospheres, in this report we investigated the link between CMV70-3P microRNA and activation of glioma stemness." (PMID 27517625, 2017). "Further studies revealed significant and positive correlation between LINC00461 and SOX2 mRNA in gliomas." (PMID 29137410, 2017). "Similar results have been reported that rapamycin decreased glioma stem cell activity and temozolomide resistance through SOX2/SOX9 expression." (PMID 28903328, 2017). "Of interest, siRNA targeting NOS2 blocked the increase in SOX2, Notch-2 and β-catenin expression in irradiated U87 glioma cells, thus inhibiting the stemness machinery for malignant progression." (PMID 28424427, 2017). "For instance, TUG1 maintains stemness features of glioma stem cells via sponging miR-145 to promote SOX2 and MYC expression." (PMID 28983240, 2017). "SOX21 was recently proposed to act as a tumour suppressor in glioma, after observations that the SOX2:SOX21 balance determines cellular choice between a stem-like state and differentiation." (PMID 29089486, 2017). "The authors showed time-dependent decrease of OCT3/4, NANOG and SOX2 expression in glioma spheres after SPP1 knockdown." (PMID 28030801, 2017). "Overexpression of SOX2 in glioblastoma cells induced GSC-like properties, suggesting a prominent role of SOX2 in glioma progression and recurrence." (PMID 29246031, 2017). "SOX-2 knockdown has been reported to inhibit the sphere generation ability in glioma cell cultures as well the dedifferentiation and the stemness phenotype thus decreasing tumorigenicity." (PMID 28424427, 2017). "GSC- cultures (2 IV grade, 1 III grade and 2 low grade glioma) expressed low levels of SOX-2 positive cells (<30%; range: 8.0–30.02%, average value: 18.9%) (grey bars)." (PMID 28424427, 2017).
glioma (continued). "Again, a positive correlation between mRNA levels of LINC00461 and SOX2 was detected in Chinese glioma samples." (PMID 29137410, 2017). "For example, NRF2 knockdown decreases self-renewal capacity of glioma stem cells by significant reduction of the expression of stem-like cell markers as Bmi1, Sox2 and Cyclin E." (PMID 28671577, 2017). "In order to verify a statistical relationship among NOS2 expression levels and SOX-2 positive cells across all glioma primary cultures and cell lines kept in St-M, a correlation analysis was conducted." (PMID 28424427, 2017). "The potential role of NOS2 as a key regulator in the aberrant upregulation of master genes such as SOX-2, involved in sustaining self-renewal of glioma initiating cells should be further investigated." (PMID 28424427, 2017). "Altogether these data show that glioma cells have a dependence on SOX2 to maintain their tumorigenic activity with GSCs displaying high levels of SOX2." (PMID 27822457, 2016). "In both in vitro and in vivo studies, it was found that endothelial cells, when cocultured with glioma cells, promoted the phenotype of CSC-like glioma cells, increasing the expression genes such as Sox2, Olig2, Bmi1, and CD133 and their tumorigenicity." (PMID 26880981, 2016). "Taken together, tunicamycin suppresses the self-renewal and tumorigenic potential of glioma-initiating cell partly through reducing Sox2 translation." (PMID 27119230, 2016). "Overexpression of Sox2 obviously abrogates the reduction in glioma-initiating cell self-renewal induced by tunicamycin." (PMID 27119230, 2016). "To date, Sox2 has been found to be expressed in a variable percentage of cells in several malignant tissues, including glioma." (PMID 27119230, 2016). "Consistently, HMGA2 is ubiquitously co-expressed with SOX2 in adherent cultured glioma-initiating cells (GICs)." (PMID 27259253, 2016). "Our published data has shown that cap binding protein eIF4E activated Sox2 translation in glioma stem-like cells." (PMID 27119230, 2016). "Deciphering the molecular circuitries controlled by SOX2 in GSCs will provide insights about glioma development, biology and possible novel molecular therapies." (PMID 27669421, 2016). "We further identified that metformin down-regulates SOX2 expression in TMZ-resistant glioma cells, reduces neurosphere formation capacity of glioblastoma cells, and inhibits GBM xenograft growth in vivo." (PMID 27791206, 2016). "Recently, it was reported that E3 ubiquitin ligase CDC20-APC interacts with and regulates SOX2 protein to promote SOX2-dependent transcription and drive glioma stem cell invasiveness and self-renewal." (PMID 27791206, 2016). "Genetic mTOR silencing or pharmacological treatment with rapamycin markedly reduced SOX2 levels in glioma cells." (PMID 27822457, 2016). "Sox2 was expressed in the spheres of glioblastoma and gliosarcoma, and also played an important role in the epithelial mesenchymal transition of glioma stem cells." (PMID 27557490, 2016). "SOX2 has been reported to promote invasion, migration, and metastasis in melanoma, colorectal cancer, glioma, gastric cancer, ovarian cancer and hepatocellular carcinoma." (PMID 27225481, 2016). "In conclusion, tunicamycin suppresses the self-renewal and tumorigenic potential of glioma-initiating cell partly through down-regulation of Sox2 translation." (PMID 27119230, 2016). "In the current study, the majority of Sox2 expression was observed in the nucleus while a few glioma cells had Sox2 localized in the cytoplasm." (PMID 26755664, 2016). "Subsequent to the finding that glioma stemness was co-regulated by Twist1 and Sox2, normal neural stem cells that acquired glioma-like invasiveness through the combined FGF2 and BMP4 pathways were found to demonstrate EMT-related features." (PMID 25605251, 2015). "The importance of SOX2 in gliomas has also been demonstrated in vivo using transplantation of high-grade oligodendroglioma cells into immunodeficient mice after SOX2 knockdown." (PMID 26580604, 2015).
glioma (continued). "These cells express nestin, vimentin, and SOX2 and show malignant orthotopic tumor growth, indicating that EGFRamp is serially-maintained in the glioma stem-cell-like subpopulation." (PMID 26381735, 2015). "Astonishingly, contrary to their assumption that SOX-2 silencing would lead to decreased migration, an increased dissemination of glioma cells was observed." (PMID 26244167, 2015). "We had similar results with each of these markers but found that Sox2 antibodies provided the clearest and most robust labeling of the cells at the borders of these non-glial tumors." (PMID 25713758, 2015). "Aberrant upregulation of these oncogenes, and in particular SOX2, gives rise to a type of CSCs known as glioma stem cells (GSCs), which are able to turn into highly proliferative cells and show multilineage potential." (PMID 26580604, 2015). "This study expands upon these functions of Sox2 in neural stem cells to include a role in reactive neural stem/progenitor cells accumulating at the interface of brain and non-glial neoplasms of the CNS." (PMID 25713758, 2015). "Among cancers Sox2 has primarily been studied for a role in oncogenesis of gliomas and it is expressed in many gliomas, most notably glioblastomas." (PMID 25713758, 2015). "Knockdown of SOX2 in GSCs of human glioblastoma, a grade IV glioma and most common primary brain tumour, ceased cell proliferation and tumourigenicity in immunodeficient mice." (PMID 26580604, 2015). "Human gliomas have shown expression of SOX2, OCT4 and NANOG, postulating the CSC theory and mutagenic transformation from normal NSCs." (PMID 26580604, 2015). "Western blot results, mRNA levels and immunohistochemical data of several human glioma specimens demonstrated greater expression of SOX2, OCT4 and NANOG in higher-grade gliomas than lower grade tumours." (PMID 26580604, 2015). "Western blot analysis demonstrated that grade IV gliomas had greater SOX2 mRNA expression than grade II gliomas." (PMID 26258069, 2015). "Here; we successfully dedifferentiated two patient-derived GBM cell lines into CSC-like cells (induced glioma stem cells, iGSCs) through expression of Oct4, Sox2 and Nanog transcription factors." (PMID 25787115, 2015). "We observed that implanted cells expressed proliferation and glioma cells markers (Ki-67 and SOX2, resp)." (PMID 24982875, 2014). "For example, we found SOX2 is upregulated by SOX4, which is consistent with previous findings that the transforming growth factor-β (TGF-β)-Sox4-Sox2 pathway is essential for glioma-initiating cells to retain their stemness." (PMID 25366337, 2014). "Self-renewal capacity of a CSC is critical and enables the maintenance of the CSC subpopulation within a tumor and SOX2 has shown to mediate this in breast, gastric, ovarian, prostate cancer, glioma, osteosarcoma, lung adenocarcinoma and NSCLC." (PMID 25114775, 2014). "We were surprised with the finding that YB-1 negatively regulates Sox2, since a previous report has described a positive correlation between YB-1 and Sox2 in glioma cells." (PMID 24885403, 2014). "Cells in glioma spheres were immunostained with anti-Sox2 (a glioma stem cell marker) and the results are shown." (PMID 24819299, 2014). "No single marker has been shown to be sufficient to confer stem-cell-like properties, thus a combination of different markers is used to identify and isolate CSC in glioma, including Nestin, Sox2 (SRY-related HMG-box gene 2) and Musashi-1 (Msi-1)." (PMID 25121761, 2014). "The delivered miR-124 and miR-145 mimics significantly decreased the luciferase activity of their respected reporter target genes, SCP-1 and Sox2, and decreased the migration of glioma cells and the self-renewal of GSCs." (PMID 23548312, 2013). "One possible explanation is that ID4 up-regulation activates SOX2 through inhibition of a microRNA, mir-9*, which is a direct negative regulator of SOX2, as shown in glioma cell lines." (PMID 23613880, 2013).
glioma (continued). "For instance, a high level of Sox2 expression detectable by immunohistochemistry was found to correlate with higher invasiveness and metastatic potential in gliomas and colorectal cancer." (PMID 23815808, 2013). "Fang's work demonstrated that SOX2 plays an important role in the carcinogenesis and development of glioma." (PMID 24565222, 2013). "qPCR was used to study the transcription levels of Nestin, Bmi-1 and Sox2 in C6 glioma cells under various concentrations of melatonin." (PMID 24137328, 2013). "Sox21 is an antagonizing partner of Sox2 and negatively regulates the expression of Sox2 in glioma cells." (PMID 22111550, 2012). "More recently, Holmberg and colleagues showed that high grade gliomas coexpress pluripotency transcription factors Oct4, Sox2, Nanog and Klf4 together with mesodermal Brachyury and endodermal Sox17 transcription factors." (PMID 22276221, 2012). "We next analyzed the effect of miR-21 on SOX2 in p19Arf−/− mouse glioma primary cultures after repression of miR-21 using locked nucleic acid (LNA)-modified antisense miR-21." (PMID 22931209, 2012). "Upon siRNA-mediated knockdown of miR-21, the levels of SOX2 in both mouse glioma cell lines and human glioblastoma cell lines strongly decreased." (PMID 22931209, 2012). "In this paper we reveal that siRNA-mediated knockdown of miR-21 led to a significant reduction of SOX2 in both mouse and human glioma cells." (PMID 22931209, 2012). "Encouraged by our previous finding of the overlapping expression pattern of miR-21 and SOX2 in the normal developing mouse brain, we performed IHC staining of mouse glioma." (PMID 22931209, 2012). "On the other hand, we found that sustained as well as transient induction of Sox21 can inhibit Sox2 expression, a result similar to that previously obtained in human glioma cell lines." (PMID 23071561, 2012). "Suppression of miR-21 resulted in a decrease of SOX2 in glioma cell cultures derived from both Gtv-a and Ntv-a mice." (PMID 22931209, 2012). "Upon irreversible depletion of miR-21 the expression of SOX2 was strongly diminished in both mouse primary glioma cultures and human glioma cell lines." (PMID 22931209, 2012). "To further explore the role of Sox2, we performed in vitro analysis with brain tumor stem cells (BTSCs) and established glioma cell lines." (PMID 22069467, 2011). "The HMG-box transcription factor Sox2 and the bHLH protein Olig2 constitute additional examples of factors commonly expressed by glioma cells and stem cells of the embryonic and adult brain." (PMID 21483788, 2011). "In the present study, we show that malignant human grade IV gliomas display significant expression of Twist1 and Sox2." (PMID 22184289, 2011). "We report for the first time, that knockdown of SOX2 impairs the invasive proteolysis-dependent migration of glioma cells." (PMID 22070920, 2011). "Taking together, these data suggested that SOX2 is also a key gene in maintaining the stemness of glioma stem cells." (PMID 21211035, 2011). "Orthotopic xenograft experiments revealed a higher tumorigenicity of U343-MG glioma cells transduced with shRNA targeting SOX2 which was characterized by increased dissemination of glioma cells." (PMID 22070920, 2011). "Our study is the first that describes the impact of SOX2-RNAi on the cell cycle and on the migratory behavior of glioma cells on the molecular and cellular level." (PMID 22070920, 2011). "In fact, we revealed that treatment with the ROCK inhibitor Y27632 led to a decrease in MLC-P levels which indicates that ROCK2 is involved in the development of the membrane protrusions occurring in the U343-MG and U373-MG glioma cells with knockdown of SOX2." (PMID 22070920, 2011). "In conclusion, for the first time, we showed that interactive and co-regulatory role of Twist1 and Sox2 necessary to maintain glioma stemness was inhibited by hUCBSC." (PMID 22184289, 2011).
glioma (continued). "In order to test the tumor initiation ability and the migratory phenotype of U343-MG cells with knockdown of SOX2 in vivo we stereotactically transplanted 5 × 105 glioma cells 5 days after transduction of shSOX2 #2378- and shLuc-vectors, respectively." (PMID 22070920, 2011). "Our data suggest that SOX2 expression preserves stem cell characteristics and on the other hand can modulate the proliferation of U343-MG and U373-MG glioma cells." (PMID 22070920, 2011). "In summary, we have confirmed SOX2 as important factor involved in the preservation of a less differentiated glioma cell phenotype." (PMID 22070920, 2011). "Glioma cells cultured in vitro initially expressed high levels of Sox2, Oct4 and Nanog (LP; low passage)." (PMID 21483788, 2011). "Herein, we aim to explore the role of SOX2 for glioma malignancy in particular its role in cell proliferation and migration." (PMID 22070920, 2011). "To evaluate this relationship, we examined seven tissue samples of grade IV gliomas (from surgical biopsy specimens) labeled with antibodies against Sox2 and Twist1." (PMID 22184289, 2011). "We therefore utilized the compound Y27632, which is known to specifically inhibit ROCK proteins and monitored its effects on SOX2-depleted U343-MG and U373-MG glioma cells using life cell imaging." (PMID 22070920, 2011). "Life cell imaging was employed in order to examine the biology of the observed morphological changes in SOX2-depleted glioma cells." (PMID 22070920, 2011). "Nonetheless, in our study we demonstrate for the first time a role of SOX2 in migration of glioma cells." (PMID 22070920, 2011). "While the proportion of Nanog+/Sox2+ cells was similar in a grade II and a grade IV tumor, the amount of Sox2+ cells expressing Oct4 was increased from below 5% in grade II gliomas to above 50% in grade IV tumors." (PMID 21483788, 2011). "(Five hGBMs 2,4,5,6 and 7 of seven glioma specimens expressed variable levels of both Sox2 and Twist1)." (PMID 22184289, 2011). "Strikingly, when we tested U343-MG glioma cells with knockdown of SOX2 in orthotopic xenografts we observed a significant decreased survival of these mice when compared to controls." (PMID 22070920, 2011). "Sox2, commonly expressed by glioma cells and stem cells of the embryonic and adult brain maintains proliferative potential of neural precursor cells, glioma-initiating cells and drives oncogenesis- associated aggressive tumor phenotype." (PMID 22184289, 2011). "Our studies on glioma stem cells treatment with human umbilical cord blood derived- mesenchymal stem cells, showed down regulation of Twist1 and Sox2 proteins, apart from other mesenchymal stem cell markers." (PMID 22184289, 2011). "Our findings suggest that SOX2 plays a role in the maintenance of a less differentiated glioma cell phenotype." (PMID 22070920, 2011). "SOX2 is a marker for gliomas in early and progressed stages, and it plays a fundamental role in the maintenance of the self‐renewal capacity of neural stem cells after they have acquired cancer properties." (PMID 20500513, 2010). "SOX2 protein expression in glioma cell lines and tumour tissues was verified by Western blot and immunofluorescence." (PMID 17375044, 2007). "The expression of SOX2 in glioma tissues, glioma cell lines as well as in the primary GBM cell preparations DD-HT4, and DD-HT6559 was also verified at the protein level." (PMID 17375044, 2007). "Human leucocyte antigen-A*0201-restricted SOX2-derived peptides were tested for the activation of glioma-reactive CD8+ cytotoxic T lymphocytes (CTLs)." (PMID 17375044, 2007). "Immunohistochemistry demonstrated SOX2 protein expression in all malignant glioma tissues investigated ranging from 6 to 66% stained tumour cells." (PMID 17375044, 2007).